MRPS16 (mitochondrial ribosomal protein S16)
Diseases named in the same sentence as MRPS16 in open-access papers (continued):
Sharing a sentence is not in itself a finding about the gene and the disease.
tumor (7 papers, 2020 to 2026). "Based on the loss/gain of function, MRPS16 promoted tumour cell growth." (PMID 38506080, 2024). "Mice with MRPS16 knockdown exhibited prolonged survival, smaller tumour volumes and less tumour weight compared to those with normal U251 cells implanted into them." (PMID 41578162, 2026). "As was shown via IVIS Spectrum in Vivo imaging system, tumour proliferation presented much less bioluminescence signals in the MRPS16‐KD group as compared with the control group, Mann–Whitney U test was used for bioluminescence data." (PMID 41578162, 2026). "There have been reports that overexpression of mitochondrial ribosomal protein S16 (MRPS16) can greatly improve the growth of tumour cells, migration and invasion abilities in many ways." (PMID 41578162, 2026). "On the contrary, it is also observed that overexpression of MRPS16 promotes tumour cell proliferation." (PMID 41578162, 2026). "Knockdown experiments of MRPS16 have shown that it can inhibit tumor cell growth, migration, and invasion, while overexpression of MRPS16 enhances these tumor characteristics." (PMID 40371222, 2025). "The reduced Ki‐67 expression in xenograft tumours of Frataxin silencing groups also implied that Frataxin silencing had the capability to counteract the MRPS16 influence on promoting cell growth." (PMID 38506080, 2024). "Collectively, PI3K/AKT/Frataxin signalling axis activation by MRPS16 was indicated to enhance tumour growth." (PMID 38506080, 2024). "Functional tests indicated that MRPS16 knocking down curbed tumour cells proliferation, migration and invasion, which was verified further by the in vivo animal experiments." (PMID 38506080, 2024). "Collectively, MRPS16 enhances tumour development through PI3K/AKT/Frataxin signalling axis activation." (PMID 38506080, 2024). "Ki‐67 IF staining was utilized for assessing the proliferative tumour index, indicating that proliferation in the MRPS16 overexpression groups was more elevated than in the control groups, suggesting that MRPS16 overexpression enhances tumour growth." (PMID 38506080, 2024). "Wu et al15 reported that the facilitation of tumour progression is attributed to MRPS16 through the activation of the PI3K/AKT/Snail signalling axis." (PMID 38506080, 2024). "MRPS16 was reported to function as an oncogene and is involved in the transformation and tumour progression." (PMID 38506080, 2024). "In H23 and H2030 cells, short hairpin RNAs (siRNAs) targeting Frataxin were utilized to investigate further its role in MRPS16‐mediated tumour cell proliferation, migration and invasion." (PMID 38506080, 2024). "Performing Ki‐67 IF staining for the purpose of assessing, the proliferative tumour index showed that proliferation in the MRPS16 knockdown groups was reduced more than in the control groups." (PMID 38506080, 2024). "The reduced Ki‐67 expression in xenograft tumours of LY294002‐treated mice also implied that PI3K/AKT signalling inhibition had the ability to counteract the MRPS16 influence on enhancing cell proliferation." (PMID 38506080, 2024). "Based on functional tests, MRPS16 overexpression advanced tumour cell proliferation, migration and invasion." (PMID 38506080, 2024). "Then, we performed CCK-8, EdU, colony formation and Transwell experiments to determine the effects of MRPS16 on tumor cell growth, migration and invasion." (PMID 32127931, 2020). "Quantitative analysis further indicated that MRPS16 protein expression levels significantly increased in tumor tissues, especially for HGG compared with NBT." (PMID 32127931, 2020). "The data showed that MRPS16 often exhibited higher expression in tumor tissues, especially for HGG, compared with NBT." (PMID 32127931, 2020). "Then, we adopted CCK-8, EdU, colony formation and Transwell experiments to determine the effects of MRPS16 on tumor cell growth, migration and invasion." (PMID 32127931, 2020).
tumor (continued). "Snail over-expression rescued the effect of MRPS16 knockdown on the suppression of tumor cell proliferation, colony formation, migration and invasion." (PMID 32127931, 2020). "It proves that MRPS16 can promote the proliferation of tumour." (PMID 41578162, 2026). "Interestingly, data analysis from the TCGA tumour database also showed again that MRPS16 was overexpressed in tumour tissues and was inversely proportional to the patient prognosis." (PMID 38506080, 2024). "Furthermore, in vivo animal experiments once again showed that overexpression of MRPS16 promotes tumour growth." (PMID 38506080, 2024). "Mechanistically, MRPS16 may enhance tumour progression through PI3K/AKT/Frataxin signalling pathway activation." (PMID 38506080, 2024). "Our data not only indicated that MRPS16 activated the PI3K/AKT/Frataxin axis to facilitate tumour cell proliferation, migration and invasion but also that MRPS16 activated PI3K/AKT signalling, which promoted Frataxin protein expression and promoted LAUD progression." (PMID 38506080, 2024). "Moreover, MRPS16‐knockdown‐mediated Frataxin overexpression was shown to restore the reduction in tumour cells proliferation, migration and invasion." (PMID 38506080, 2024). "And the aberrant expression of mitochondrial ribosomal protein S16 (MRPS16) could facilitate tumor cell growth, migration, and invasion via activating the PI3K/AKT signaling pathway." (PMID 34692528, 2021). "Therefore, our data suggest that MRPS16 promotes tumor progression by modulating the protein expression of Snail." (PMID 32127931, 2020). "In addition, these data further clarified that MRPS16 facilitated tumor cell growth, migration and invasion by activating the PI3K/AKT/Snail axis." (PMID 32127931, 2020). "The data showed that MRPS16 over-expression facilitated tumor cell growth, migration and invasion." (PMID 32127931, 2020). "The results indicated that MRPS16 knockdown could inhibit tumor growth and that Snail over-expression could abrogate the MRPS16 knockdown-mediated inhibition of tumor growth." (PMID 32127931, 2020). "Conversely, MRPS16 over-expression increased tumor cell proliferation." (PMID 32127931, 2020). "Conversely, MRPS16 over-expression increased tumor cell growth, migration and invasion." (PMID 32127931, 2020). "Collectively, all the data suggested that MRPS16 knockdown could inhibit tumor growth and that Snail over-expression could abrogate the effect in vivo." (PMID 32127931, 2020). "In addition, MRPS16 depletion also inhibited tumor growth in mice." (PMID 34361072, 2021). "Furthermore, we observed that the decrease in tumor cell growth, migration, invasion and Snail expression mediated by MRPS16 knockdown could be rescued by Snail over-expression." (PMID 32127931, 2020). "The tumours in the mice inoculated with MRPS16‐OE + NFATC2‐KD U87 cells grew slower than the other two groups, as indicated by the bioluminescence of the tumour, and the overall survival is higher than these two groups." (PMID 41578162, 2026). "Wnt pathway, which is basically related to both MRPS16 and NFATC2, is an important signally pathway in the regulation of tumour proliferation and progression." (PMID 41578162, 2026). "Wang et al15 revealed that MRPS16 enhances tumour cell growth by PI3K/AKT signal path, demonstrating the critical role played by MRPS16 in biological processes further." (PMID 38506080, 2024). "Moreover, the examined association between MRPS16 mRNA levels and clinicopathological characteristics in 98 LAUD samples showed that the MRPS16 mRNA expression level had a significant correlation to the tumour size (p = 0.002), lymph node metastasis (p < 0.0001) and TNM stage (p = 0.002)." (PMID 38506080, 2024).
tumor (continued). "In in vivo experiments with BABL/c mice inoculated with U251 and U87 cells intracranially, the knockdown of MRPS16 and overexpression of NFATC2 led to the tumours in the mice exhibiting a high growth rate compared with mice inoculated with cells that only had the MRPS16 gene knocked down." (PMID 41578162, 2026). "But compared to the cells that were not treated with U87, tumour volume and tumour weight of the mice were much less when the cells infected with MRPS16‐KD U87, Statistical significance was assessed using Student's t‐test." (PMID 41578162, 2026). "Compared to the MRPS16‐KD U87 cells‐inoculated mice, the mice inoculated with MRPS16‐KD + NFATC2‐OE U87 cells had significantly larger and faster growing tumours, but they did not have statistically affected overall survival." (PMID 41578162, 2026).
mitochondrial disease (1 paper, 2022). "Mitochondrial disease-causing mutations were found in thirteen small ribosomal subunit mitoribosomal proteins (MRPS1, MRPS2, MRPS6, MRPS7, MRPS9, MRPS11, MRPS14, MRPS16; MRPS22, MRPS23, MRPS25, MRPS34, MRPS39) and four large ribosomal mitochondrial proteins (MRPL3, MRPL12, MRPL24, MRPL44)." (PMID 36140315, 2022).
MRPS16 also shares sentences with these, for which no sentence is quoted: lactic acidosis (1 paper); lung adenocarcinoma (1); lung carcinoma (1).